INS (insulin)
Diseases named in the same sentence as INS in open-access papers (continued):
Sharing a sentence is not in itself a finding about the gene and the disease.
Obesity (continued). "To identify microbial taxa that correlate with impaired insulin clearance during diet-induced obesity, we compared the fecal microbiome characteristics in the Chow-R and HFD-R mice after 6 weeks on a chow diet and after 2 weeks of HFD feeding." (PMID 32860984, 2020). "The PI3K-AKT signaling pathway plays an important role in the control of insulin metabolism in obesity and T2DM." (PMID 32796637, 2020). "There is an ongoing randomized clinical trial of FMT for obesity in adolescents that will assess long-term BMI changes, adiposity, and insulin sensitivity in male and female participants." (PMID 33329193, 2020). "Our results suggested that obesity and/or a high fat diet lead to oxidative stress and resistance to insulin in the cardiac tissue of obese mice." (PMID 32215468, 2020). "In the present study, we found that lingonberry supplementation prevented high-fat diet induced adverse effects on blood cholesterol, glucose and insulin levels as well as visceral fat gain in a murine model of obesity." (PMID 32379797, 2020). "These alterations in different studies of citrate levels suggest a closed relation with the disturbances in glucose and insulin in obesity." (PMID 32197513, 2020). "Ginsenosides Rb1, Rg3, CK, and Rg1, can improve insulin sensitivity and inhibit the occurrence of obesity by activating the AMPK pathway." (PMID 33841133, 2020). "On the contrary, systemic levels of ATX, in these same mice, has been shown to affect obesity-driven cardiomyocyte dysfunction and hepatic steatosis, both involving deregulated insulin-glucose homeostasis." (PMID 32240164, 2020). "They showed that ceramide concentrations were elevated specifically in low-density lipoproteins (LDL) of T2D patients compared with insulin-sensitive individuals, independently of obesity." (PMID 32849282, 2020). "MC4R has been associated with key components of appetite, food intake, nutrient absorption, thermogenesis, energy expenditure, insulin secretion, obesity, and lipid metabolism." (PMID 32390949, 2020). "A study with BPL1 showed improvements in insulin sensitivity in adult subjects with simple obesity, while another clinical study with the B420 strain showed no improvements." (PMID 33066107, 2020). "NLRP3-dependent IL-1β secretion has been shown to impair pancreatic beta cell function, adipocyte function, and insulin sensitivity, promoting the progression of obesity and insulin resistance." (PMID 32751530, 2020). "Obesity is linked to the development of T2DM and cardiovascular diseases possibly through detrimental effects on insulin and glucose metabolism." (PMID 33212990, 2020). "Dysregulation of the adipo-insular axis in obesity leads to a rise of basal plasma levels of insulin and leptin and development of compensatory peripheral tissue resistance to both hormones." (PMID 32092909, 2020). "We discovered that dietary ABA increases insulin sensitivity and suppresses obesity-related inflammation in obese/diabetic db/db mice." (PMID 32591558, 2020). "Obesity, gluconeogenesis, and adipose tissue insulin signaling were only partially reversed in nitrite supplemented iNOS−/− mice." (PMID 32806494, 2020). "Another study showed B. acidifaciens to be enriched in normal human subjects, compared to patients with inflammatory bowel disease, and B. acidifaciens increased insulin sensitivity and prevented further obesity." (PMID 32811478, 2020). "In the light of the results obtained, it is worth emphasizing that the administration of recombinant vaspin to mice with diet-induced obesity led to an improvement in glucose tolerance and an increase in insulin sensitivity." (PMID 32917052, 2020). "The smaller relative decrease from baseline in insulin secretion in patients with T2DM suggests that in these individuals with severe obesity, β-cells are operating at close to their functional limit." (PMID 31720686, 2020).
Obesity (continued). "This is consistent with previous reports of the beneficial and deleterious effects of insulin in obesity and other insulin-resistant syndromes." (PMID 32029228, 2020). "Pharmacological inhibition of ERK improves insulin sensitivity in both diet-induced obesity and ob/ob mice." (PMID 32576931, 2020). "Mechanisms linking obesity and prostate cancer (PC) include increased insulin signaling, persistent inflammation, and altered adipocytokines secretion." (PMID 32326011, 2020). "In the obesity group, insulin and adiponectin had statistically higher concentrations (p<0.05), while HDL-C, total- and HMW-adiponectin were lowest." (PMID 31552725, 2020). "Specifically, there is strong evidence for the role of chronic inflammation in mediating the obesity–cancer relationship, while the role of insulin and IGF appears to be moderate." (PMID 32197341, 2020). "High levels of NOV have been attributed to obesity, and its ablation reduced inflammation and fat mass and increased insulin sensitivity." (PMID 31906399, 2020). "Follistatin is a soluble glycoprotein secreted by BAT that can blockade the activities of some members of the transforming growth factor (TGF) family, induce insulin sensitivity and prevent diet-induced obesity." (PMID 33227979, 2020). "Obesity induces insulin, IGFs, leptin, IL-6, TNF-α, CCL2, and PAI-1, reduces adiponectin, and disturbs gut microbiota and bile acid homeostasis." (PMID 32486076, 2020). "Model systems have shown the inhibition of ceramide biosynthesis to antagonize obesity and improve insulin sensitivity." (PMID 32641420, 2020). "In the context of obesity, insulin becomes less efficient as a consequence of the development of insulin resistance by the target tissues." (PMID 32492936, 2020). "At the onset of obesity, the excessive levels of these two hormones lead to the impairment of their functions in target tissues, resulting in insulin/leptin resistance." (PMID 33218042, 2020). "In contrast, JMJD1C-LKO mice on HFD remained insulin-sensitive, protected from diet-induced obesity-related IR, even when these mice still manifested higher WAT mass." (PMID 32034158, 2020). "The serum levels of obesity-related metabolic signaling molecules, including insulin, adiponectin, lipopolysaccharide (LPS) and the cytokines interleukin (IL)-1β and tumor necrosis factor (TNF)-α, were markedly improved." (PMID 32244807, 2020). "Previous studies confirm that vaspin can improve glucose metabolism and insulin sensitivity in obesity, attenuate adipose tissue inflammation, taken together, partially ameliorate the adverse effects of DIO." (PMID 31993071, 2020). "In a multivariate analysis adjusted for the year of study, age, and gender, prominent factors associated with increased IR or subclinical inflammation were obesity levels measured using waist circumference, glycated haemoglobin, and fasting insulin levels." (PMID 32566678, 2020). "High-fat feeding and obesity induce CEPT expression, whereas CEPT-deficient mice have improved insulin sensitivity." (PMID 32399287, 2020). "Insulin granule density was reduced in beta cells of maternal obesity-exposed offspring of both sexes (p < 0.01)." (PMID 31773193, 2020). "There is also evidence of a blunted exercise-induced reduction in insulin concentration with obesity." (PMID 32120832, 2020). "Our results demonstrate that in participants with severe obesity and NFG, reduced S(I) is partially compensated by increased insulin secretion and that short-term weight loss improves S(I) and decreases insulin secretion towards normal." (PMID 31720686, 2020). "The finding that obesity determines a chronic hypoxic state in adipose tissue and several other tissues, which is common to insulin-resistant conditions, has been widely reviewed." (PMID 33266015, 2020). "IL-10 seems to attenuate obesity-mediated inflammation and improve insulin sensitivity in skeletal muscle." (PMID 32272872, 2020).
Obesity (continued). "The faulty insulin sensitivity of adipose tissues, connects the obesity with other chronic diseases like diabetes, hyperlipidemia, arthritis, hypertension, cardiovascular disease, ischemic stroke, hyperglycemia and different types of cancer." (PMID 32027667, 2020). "Prolonged obesity leads to β-cell exhaustion, culminating in a reduced insulin response and an inability to maintain normoglycemia." (PMID 33290405, 2020). "In this report, we show that genes involved in obesity and insulin pathways are upregulated after RYGB." (PMID 32599690, 2020). "Oral ingestion of alanine also increased insulin (iAUC, 42.67 μU/mL/min), and decreased glucose concentrations (iAUC, −10.49 mg/dL/min) from baseline in people with obesity." (PMID 33096658, 2020). "Further, during aging these PPARβ/δ KO mice display adipocyte hypertrophy and glucose intolerance, and are insulin resistant, which is reminiscent of metabolic disorders such as obesity and diabetes in mice and humans." (PMID 33137899, 2020). "Various studies have shown that mitochondrial function and biogenesis are impaired in type 2 diabetes, obesity, and insulin-resistant adipose tissue." (PMID 33841133, 2020). "A better understanding of the direct insulin action on hepatocyte metabolism in physiological conditions and in obesity is therefore necessary to unravel the link between obesity, insulin resistance, and fatty liver disease." (PMID 32694512, 2020). "Lactobacillus acidophilus NS1 can alleviate HFD-induced obesity in mice by improving lipid metabolism and insulin sensitivity through an AMP-activated protein kinase." (PMID 32218367, 2020). "The leptin-deficient (ob/ob) or (Lepob/Lepob) mouse model develops hyperphagia, obesity, transient hyperglycaemia, high serum insulin, elevated numbers of pancreatic beta cells, lowered LH, GH in the serum but higher hypophyseal Prl protein content." (PMID 32183843, 2020). "Obesity-related insulin resistance leads to the increased secretion of insulin, which in turn leads to a state of hyperinsulinemia." (PMID 32069845, 2020). "Similar results were obtained for correlation with markers of obesity (insulin, CRP, and leptin) with estradiol and estrone (−0.15 to 0.12; p = 0.11–0.82)." (PMID 32566743, 2020). "One analysis utilized a polygenic animal model of diet induced obesity to examine the function of insulin in respiratory tract hyper‐responsiveness related to obesity." (PMID 33145961, 2020). "After weight loss, β-cell function tends to remain lower, suggesting that the observed increase in insulin secretion is inadequate to restore β-cell function to normal levels in participants with severe obesity and T2DM." (PMID 31720686, 2020). "For instance, study populations with obesity class 1 (BMI 30–34.9 kg/m2) and class 3 (BMI ≥ 40 kg/m2) are afflicted differently by hyperinsulinemia, hyperleptinemia, insulin and leptin resistance or low ghrelin levels." (PMID 32721994, 2020). "FGF21 directly acts in the brain to increase the insulin sensitivity and metabolic rate in rats with diet-induced obesity." (PMID 32724479, 2020). "Insulin use was positively correlated with isolated fasting and combined abnormalities, even after adjustment for maternal age, ethnicity, parity, and obesity." (PMID 32987806, 2020). "Obesity is characterized by a state of chronic, unresolved inflammation in insulin-targeted tissues." (PMID 32180905, 2020). "Paradoxically, the in vivo myeloid cell-specific deletion of Ncor1 repressed inflammatory gene expression and improved insulin sensitivity in a diet-induced obesity mouse model." (PMID 33117357, 2020). "For example, the method clearly picks up fibroblast growth factor 21 (FGF21), a hormone that is known to have elevated levels in insulin-resistant morbidities such as obesity and T2DM." (PMID 33204460, 2020). "Together, these data support a model in which the intestinal microbiota contributes to impaired insulin clearance during chronic diet-induced obesity." (PMID 32860984, 2020).
Obesity (continued). "Mice heterozygous for a mutation in Inpp5k show increased AKT phosphorylation in skeletal muscle as well as increased insulin sensitivity and reduced diet-induced obesity." (PMID 33276499, 2020). "Overall, these results provide strong evidence that adropin overproduction improves insulin sensitivity and glucolipid metabolism in obesity." (PMID 32012786, 2020). "Although it continues to be an area of debate, recent animal and genetic studies suggest that insulin dysregulation plays a major role in obesity and metabolic disorders." (PMID 31846028, 2020). "Studies have demonstrated that A-FABP is crucial to lipid metabolism, insulin sensitivity, and the activation of inflammatory pathways related to obesity, MetS, type 2 DM, and atherosclerosis." (PMID 33080960, 2020). "Mice with diet-induced obesity switched to an LCD were also glucose intolerant but they had similar insulin tolerance to those switched to chow." (PMID 33187118, 2020). "One of obesity's main links to the problem of cancer is that it usually involves an increase in visceral fat, which leads to significantly increased insulin hormonal activity." (PMID 32742493, 2020). "In WD mice, L‐NAME tended to increase insulin secretion highlighting the deleterious effect of early obesity on nervous insulin control secretion." (PMID 31922022, 2020). "These pathways are activated for macrophage-beta cell interactions, which to some extent, explains the transference of vesicles containing insulin from beta cells to macrophages, which is greatly augmented in obesity." (PMID 33182622, 2020). "Deletion of adipocyte MCP‐1 in vivo protected against obesity‐induced insulin and glucose resistance, indicating the importance of this pathway in the regulation of glucose metabolism." (PMID 32892401, 2020). "Individuals with android-type obesity compared to gynoid-type obesity have higher fasting insulin and glucose levels." (PMID 32384681, 2020). "A large feeding study reported that total energy expenditure (TEE) was greater on a low- versus high-carbohydrate diet, supporting the carbohydrate-insulin model of obesity." (PMID 32435054, 2020). "Insulin is the prime mediator of metabolic homeostasis, which is impaired in obesity, and this impairment potentiates amyloid-β (Aβ) accumulation and the formation of neurofibrillary tangles (NFTs)." (PMID 33384592, 2020). "The key symptoms of asinine metabolic syndrome (AMS), similar to horses, are obesity, insulin dysregulation, and laminitis." (PMID 33302557, 2020). "Resistin is well known to decrease insulin sensitivity and enhance adipocyte inflammation, contributing to the lipid dysfunction in obesity." (PMID 33489104, 2020). "Evidence suggests that the gut microbiota plays a role in obesity as it contributes to different mechanisms, such as metabolism, body weight and composition, inflammatory responses, insulin signalling, and energy extraction from food." (PMID 32363032, 2020). "Tan I prevented HFD-induced obesity via the inhibition of early adipogenesis and thus ameliorated glucose metabolism and insulin sensitivity." (PMID 32349456, 2020). "Obesity, AD, and diabetes concomitantly share common features like brain atrophy, reduced cerebral glucose, and CNS insulin resistance." (PMID 32455946, 2020). "In obesity, elevated levels of miR-222, a negative regulator of insulin sensitivity in adipocytes, were found both in adipose tissue and in circulating small EVs." (PMID 33339409, 2020). "These subjects were randomized based on obesity and the dose of glimepiride with a 1:1 ratio of insulin detemir (prolonged-action analog) and Biphasic Insulin (rapid-action analog)." (PMID 33187372, 2020). "This does not appear to be due to a decrease in the expression of InsR in NPY neurons; therefore, obesity in females somehow attenuates insulin signaling specifically in presympathetic ArcN neurons." (PMID 32160920, 2020).
Obesity (continued). "In another study, elevated levels of TAG and obesity in IP3R-Drosophila mutants were also rescued after insulin expression, further suggesting the involvement of ILPs in lipid metabolism." (PMID 32457651, 2020). "Obesity occurs through enlarged adipocyte cells as well as through an increase in the number of these adipose cells, both processes that are regulated by insulin levels." (PMID 32742493, 2020). "Cholesteryl ester transfer protein (CETP), a protein involved in replacing lipids between lipoproteins, improves insulin sensitivity in obesity through increased cholesterol delivery to liver and activation of bile acid-sensitive pathways." (PMID 32586392, 2020). "Despite the specific mechanisms not being completely understood, the primary method by which obesity links to T2DM is through insulin resistance." (PMID 32903449, 2020). "LCR rats have progressed to a phenotype of metabolic syndrome including obesity, elevated blood glucose, and high levels of insulin, triglycerides and free fatty acids." (PMID 33108389, 2020). "By improving the expression of GLUT4 protein and improving the insulin sensitivity of all organs and tissues, and promoting the uptake and utilization of glucose and free lipids in all organs, obesity can be managed from various aspects." (PMID 33841133, 2020). "The set point of body weight is the balance between energy intake and energy expenditure, and the central role of insulin axis in energy imbalance can contribute to the pathogenesis of obesity." (PMID 32309765, 2020). "Mice with skeletal muscle-specific deletion of JNK1 are unaffected by diet-induced obesity but are insulin sensitive." (PMID 33179019, 2020). "Elevations in circulating insulin were evident in both mouse models of obesity used in our study: genetic (EMD mice) and diet-induced obesity model (HFD-fed wt mice)." (PMID 31937343, 2020). "Altogether, the data indicate that, although NQO1-Tg mice on HFD develop obesity, they remain insulin sensitive while being protected from liver steatosis." (PMID 33298924, 2020). "These were accompanied by increased FI and lower energy expenditure (EE), leading to obesity, along with increased leptin and insulin levels and HOMA." (PMID 32576879, 2020). "Under certain physiological conditions, like pregnancy and obesity, target tissues become resistant to the action of insulin." (PMID 32286361, 2020). "Significant improvements were observed in measures of obesity, as well as static and dynamic measures of glucose, insulin, C-peptide and HOMA." (PMID 32067166, 2020). "During the development of obesity in response to H.F.D, a clear change was observed mostly as a significant (P < 0.05) increase in fasting glucose and insulin levels started at week 4 and week 6 respectively compared to normal diet group." (PMID 32366215, 2020). "Obesity is a complex metabolic disorder that often leads to a decrease in insulin sensitivity, chronic inflammation, and overall decline in human health and well‐being." (PMID 32776502, 2020). "With regards to impaired myocardial glucose utilization in obesity/T2D, cardiac myocytes isolated from adult ob/ob and db/db mice exhibit reduced insulin-stimulated Akt phosphorylation and 2-deoxyglucose uptake." (PMID 33041869, 2020). "In contrast, the induction of Xbp1s in POMC neurons protects against diet-induced obesity and improves leptin and insulin sensitivity." (PMID 32313051, 2020). "For women, insulin sensitivity that coincides with obesity inhibits ovulation and reduces the quality of eggs and embryos, which is thought to have adverse effects on implantation." (PMID 32684824, 2020). "On the other hand, the reverse situation also appears to be true, since it was observed that insulin and obesity stimulates the gene expression of TNF-α and IL-6 in adipose tissue." (PMID 32187268, 2020).